TIMM13 (translocase of inner mitochondrial membrane 13)
Description:
Mitochondrial intermembrane chaperone that participates in the import and insertion of some multi-pass transmembrane proteins into the mitochondrial inner membrane. Also required for the transfer of beta-barrel precursors from the TOM complex to the sorting and assembly machinery (SAM complex) of the outer membrane. Acts as a chaperone-like protein that protects the hydrophobic precursors from aggregation and guide them through the mitochondrial intermembrane space. The TIMM8-TIMM13 complex mediates the import of proteins such as TIMM23, SLC25A12/ARALAR1 and SLC25A13/ARALAR2, while the predominant TIMM9-TIMM10 70 kDa complex mediates the import of much more proteins.
Synonyms: TIM13B; TIMM13A; TIMM13B; Tim13; ppv1
Tractability: Antibody: UniProt places it where antibodies can reach, with high confidence. PROTAC: ubiquitination databases record sites on it; its protein half-life has been measured.
Gene: Protein-coding gene on chromosome 19 (2,425,625 to 2,427,588, reverse strand). Ensembl gene ENSG00000099800.
Subcellular location: Mitochondrion inner membrane
Subcellular location (Human Protein Atlas): Mitochondria; Nucleoli fibrillar center
Pathways (Reactome):
Protein localization: Mitochondrial protein import
Gene Ontology:
Molecular function: protein binding; zinc ion binding
Biological process: protein insertion into mitochondrial inner membrane
Cellular component: mitochondrial inner membrane; mitochondrial intermembrane space chaperone complex; mitochondrion; mitochondrial intermembrane space
Genetic constraint (gnomAD): Loss-of-function variants: 8 observed, 9.38 expected, observed/expected ratio (o/e) 0.85, 90% interval 0.5 to 1.52. That is too few expected variants to judge how well the gene tolerates losing a copy. Missense variants: 147 observed, 134.83 expected, observed/expected ratio (o/e) 1.09, 90% interval 0.95 to 1.25. Synonymous variants: 68 observed, 51.92 expected, observed/expected ratio (o/e) 1.31, 90% interval 1.08 to 1.6.
Homologues: Orthologues: chimpanzee TIMM13 (100% identical), mouse Timm13 (95% identical), tropical clawed frog timm13 (89% identical), zebrafish timm13 (86% identical), pig TIMM13 (83% identical), rat Timm13 (79% identical), Drosophila melanogaster CG34132 (55% identical), Drosophila melanogaster Tim13 (53% identical), Caenorhabditis elegans tin-13 (40% identical), Drosophila melanogaster CG42302 (32% identical).
Diseases named in the same sentence as TIMM13 in open-access papers:
TIMM13 is named in the same sentence as 37 diseases in open-access papers, as found by Europe PMC text mining. Sharing a sentence is not in itself a finding about the gene and the disease. The quoted sentences say what the papers report.
breast carcinoma (3 papers, 2022 to 2025). "Recent studies have identified overexpression of TIMM8A and TIMM13 in various tumor types, including breast cancer, endometrial carcinoma, osteosarcoma, and cutaneous melanoma." (PMID 40918471, 2025). "In a study of breast cancer, significant changes were found in the level of Timm13, but the specific mechanism was not clarified." (PMID 36899394, 2023).
osteosarcoma (3 papers, 2023 to 2025). A usually aggressive malignant bone-forming mesenchymal neoplasm, predominantly affecting adolescents and young adults. "Similarly, TIMM13 has been recently identified to be associated with tumorigenesis in some certain malignancies, including skin cutaneous melanoma and osteosarcoma." (PMID 40918471, 2025). "The primary human osteosarcoma cells, pOS-1, were infected with the lentiviral particles with shRNAs targeting human TIMM13, namely shTIMM13-S1 or shTIMM13-S2 (with non-overlapping sequences)." (PMID 37407582, 2023).
skin cutaneous melanoma (3 papers, 2022 to 2025). "In spite of this, it is still unknown how TIMM13 interacts with skin cutaneous melanoma (SKCM) and tumor-infiltrating lymphocytes (TILs)." (PMID 36061054, 2022).
deafness (2 papers, 2023 to 2025). An inherited or acquired condition characterized by the complete loss of the ability to hear from one or both ears. "Timm13 is associated with neuroblastoma, lung disease, nasopharyngeal carcinoma, hepatocellular carcinoma and deafness/dystonia syndrome." (PMID 36899394, 2023). "When the DDP1/Timm8a-Timm13 complex assembly is defective, it can cause human deafness/dystonia syndrome." (PMID 36899394, 2023). "Subsequently, a case report also analyzed the relationship between deafness/dystonia syndrome and DDP1/Timm8a-Timm13." (PMID 36899394, 2023).
deafness dystonia syndrome (2 papers, 2022 to 2023). An X-linked recessive neurodegenerative syndrome characterized by clinical manifestations commencing with early childhood onset hearing loss, followed by adolescent onset progressive dystonia or ataxia, visual impairment from early adulthood onwards and dementia from the 4th decade onwards. "Timm13 is associated with Mohr-Tranebjaerg Syndrome and Visual Cortex Disease." (PMID 36061054, 2022).
liver fibrosis (2 papers, 2023 to 2025). "The results of the present study showed that Timm13, a translocase of the mitochondrial inner membrane has a significant influence on liver fibrosis; however, the underlying mechanism has yet to be fully elucidated." (PMID 36899394, 2023). "Certain TIMs are linked to fibrotic diseases like Timm13 in liver fibrosis." (PMID 41462614, 2025). "In the present study, we used bioinformatics to analyze significant liver fibrosis-related genes, and then explored the relationship between Timm13 and liver fibrosis using cellular experiments and animal models." (PMID 36899394, 2023). "Finally, we examined the mechanism of Timm13 in regulating liver fibrosis by targeted knockdown of Timm13." (PMID 36899394, 2023). "Based on this study, Timm13 may have a profound influence on liver fibrosis." (PMID 36899394, 2023). "The results showed that Timm13 is closely related to liver fibrosis and silencing Timm13 significantly reduced the expression of profibrogenic genes and apoptosis related genes, which will provide novel ideas and targets for the clinical diagnosis and treatment of liver fibrosis." (PMID 36899394, 2023). "As the role of Timm13 in liver fibrosis was not reported, we therefore selected Timm13 for the following experiments." (PMID 36899394, 2023). "A previous study suggested that Timm13 is highly expressed in the brain and liver; however, there are no reports on the role of Timm13 in liver fibrosis nationally and internationally, and there are few reports on the role of Timm13 in other diseases." (PMID 36899394, 2023). "However, the relationship between translocase of the mitochondrial inner membrane or Timm13 and liver fibrosis has not been reported." (PMID 36899394, 2023).
melanoma (2 papers, 2022 to 2025). A malignant, usually aggressive tumor composed of atypical, neoplastic melanocytes. "The IHC staining results showed that TIMM13 showed higher expression levels in melanoma tissues (n = 25) than in normal skin tissues (n = 15)." (PMID 36061054, 2022). "We next explored the protein expression levels of TIMM13 between melanoma and normal skin tissues." (PMID 36061054, 2022). "TIMM13 was highly expressed in melanoma tissue samples than in normal samples." (PMID 36061054, 2022).
neuroblastoma (2 papers, 2023). Neuroblastoma (NB) is the most common solid, extracranial childhood tumor. "TIMM13 is a translocation enzyme involved in introducing metabolite transporters from the cytoplasm into the mitochondrial inner membrane, and it is a direct target of miR-34a, which is involved in neuroblastoma, with poor clinical results." (PMID 36901944, 2023).
auditory neuropathy (1 paper, 2022). A hearing disorder characterized by impaired transmission of signals through the auditory nerve, resulting in mild to severe hearing loss and poor speech perception. "Previous research has established that the proportion of TIMM8A mutation in the population with auditory neuropathy was 1.8 %, and the deafness-myotension disorder-optic neuropathy (DDON) syndrome was caused by the unassembled DDP1/TIMM8a-TIMM13 complex in mitochondria." (PMID 36207751, 2022).
lung carcinoma (1 paper, 2025). "The analysis revealed that lung cancer patients with high expression of either TIMM8A or TIMM13 exhibited a worse overall survival rate." (PMID 40918471, 2025). "Our research demonstrates significant overexpression of both TIMM8A and TIMM13 in lung cancer tissues, correlating with aggressive clinical pathological features and poor prognosis." (PMID 40918471, 2025).
sarcoma (1 paper, 2023). A usually aggressive malignant neoplasm of the soft tissue or bone. "The Cancer Genome Atlas (TCGA) database was consulted next and Kaplan–Meier survival results revealed that high TIMM13 expression in sarcoma patients tended to have a poor prognosis (P = 0.09)." (PMID 37407582, 2023). "Significantly, high TIMM13 expression in sarcoma patients has a poor prognosis." (PMID 37407582, 2023).
triple-negative breast carcinoma (1 paper, 2023). An invasive breast carcinoma which is negative for expression of estrogen receptor (ER), progesterone receptor (PR), and human epidermal growth factor receptor 2 (HER2). "Interestingly, subsequent study showed that Timm13 highly predicted the overall survival (OS) and relapse-free survival (RFS) of basal breast cancer, and was identified as one of the essential genes for triple-negative breast cancer (TNBC) through transcriptomics." (PMID 36899394, 2023).
cancer (5 papers, 2020 to 2025). A tumor composed of atypical neoplastic, often pleomorphic cells that invade other tissues. "TIMM13 was strongly associated with sample type, subgroup, cancer stage, lymph node stage, and worse survival." (PMID 36061054, 2022). "The differential expression of TIMM13 in tumor and normal tissues were studied by RNA-seq data of different types of cancer from TCGA." (PMID 36061054, 2022). "According to Xiantao tool, we found that the expression of TIMM13 upregulated in almost all cancer tissues such as ACC, BLCA and SKCM, but downregulated in KIRC, LAML and PCPG." (PMID 36061054, 2022). "We found that TIMM13 was abnormally expressed in the tissues of various malignant tumors." (PMID 36061054, 2022). "Thus far, TIMM13 has not been linked to cancer, so our data suggest a plausible role for this gene in TNBC response to NAC." (PMID 36142814, 2022).
tumor (5 papers, 2022 to 2025). "TISIDB and Tumor Immune Estimation Resources (TIMER) databases were applied to explore the association between TIMM13 and tumor infiltration immune cells." (PMID 36061054, 2022). "TIMM13 mRNA and protein levels in the human OS tumor tissues were significantly higher than those in the matched adjacent normal bone tissues." (PMID 37407582, 2023). "However, the possible function of TIMM13 in regulating tumor immunity and its clinical significance in SKCM are still unknown." (PMID 36061054, 2022). "The gene expression profiles suggested that the expression levels of CDC20, UQCRH, TIMM10, TIMM13, POLR2L, and NDUFAB1 were upregulated in tumor tissue." (PMID 36901944, 2023). "This research revealed the important function of TIMM13 in SKCM, and then the possible relationship and possibility of TIMM13 regulating tumor invasion of immune cells." (PMID 36061054, 2022). "It was also suggested that TIMM13 played an important role in the recruitment and regulation of TILs in SKCM, and its molecular mechanism and role in the regulation of tumor microenvironment deserve further study." (PMID 36061054, 2022). "Therefore, whether the expression of TIMM13 was related to tumor prognosis needs further study." (PMID 36061054, 2022). "Similar results were obtained by detecting CD8 + T lymphocyte infiltration using the TIMER database, suggesting that TIMM13 could play a key role in inhibiting SKCM immune infiltration and was related to tumor microenvironment." (PMID 36061054, 2022).
neurodegenerative disease (2 papers, 2021 to 2023). A disorder of the central nervous system characterized by gradual and progressive loss of neural tissue and neurologic function. "In addition, it has been reported that the neurodegenerative disease Mohr–Tranebjaerg syndrome is caused by mutation of Timm8a, which forms a complex with Timm13, indicating that Timm13 is related to neurodegenerative diseases." (PMID 36899394, 2023). "However, it is known that the neurodegenerative disease, Mohr–Tranebjaerg syndrome, occurs due to a mutation in TIMM8A, which acts as a complex with TIMM13, suggesting its association with neurodegenerative disease." (PMID 34685681, 2021).
heart disease (1 paper, 2021). "The remaining proteins, i.e., EEF1D, TIMM13, and PMPCB, are involved in transferring aminoacyl-tRNAs, regulating heat-shock response, and maintaining mitochondrial functions, but their roles in heart disease contexts have not been investigated." (PMID 34211507, 2021).
TIMM13 also shares sentences with these, for which no sentence is quoted: infection (15 papers); co-infection (4); Alzheimer disease (3); hepatocellular carcinoma (2); Stillbirth (2); viral infection (2); abortion (1); autism (1); cystic fibrosis (1); endometrial carcinoma (1); hemophilia (1); Hernia (1); Infertility (1); lung disease (1); metastatic cancer (1); microcephaly (1); nasopharyngeal carcinoma (1); neurodevelopmental disorder (1); Obesity (1); pyrexia (1); spastic hemiplegia (1).